LINC00649 (long independently transcribed non-coding RNA 649)
Synonyms: TCONS_00028768; lnc-ITSN1-2; LINC00650; LOC101928126
Gene: Long non-coding RNA gene on chromosome 21 (33,915,534 to 34,039,762, forward strand). Ensembl gene ENSG00000237945.
Diseases named in the same sentence as LINC00649 in open-access papers:
LINC00649 is named in the same sentence as 12 diseases in open-access papers, as found by Europe PMC text mining. Sharing a sentence is not in itself a finding about the gene and the disease. The quoted sentences say what the papers report.
bladder cancer (3 papers, 2022 to 2023). "LINC00649, which is located in the cytoplasm of bladder cancer, promotes the progression of bladder cancer by binding to miR-15a-5p to increase the expression of HMGA1 at the posttranscriptional level." (PMID 35864955, 2022). "We found that LINC00649 and AC011503.2 were highly expressed in bladder cancer tissues, LINC00649 was mainly distributed in the cytoplasm, and AC011503.2 was distributed primarily in the nucleus." (PMID 36300088, 2022). "In a human bladder cancer chip, we examined the expression and cellular localization of LINC00649 and AC011503.2." (PMID 36300088, 2022). "A recent study found that linc00649 is a basement membrane-related lncRNA and is correlated with clinical prognosis based on analysis of transcriptional and clinical data of bladder cancer from the TCGA, GEO and BM-BASE databases, revealing that linc00649 is a potential biomarker of BLCA." (PMID 36831352, 2023). "The study showed that AC004034.1, AC011503.2, LINC00649 and LINC02321 were significantly elevated in human BCa cells, NR2F1-AS1, SETBP1-DT and AC093010.2 were significantly reduced in human bladder cancer cells." (PMID 36300088, 2022).
lung squamous cell carcinoma (3 papers, 2023 to 2025). "Recently, LINC00649 has been revealed to interact with TAF15 to facilitate the progression of lung squamous cell carcinoma by enhancing MAPK6 expression and activating the MAPK signaling pathway." (PMID 36895010, 2023). "For instance, a study unveiled the involvement of LINC00649 in recruiting TAF15 to stabilize MAPK6 expression, thereby promoting the progression of lung squamous cell carcinoma through activation of the mitogen-activated protein kinase (MAPK) signaling pathway." (PMID 39735666, 2025). "LINC00649 was revealed to recruit TAF15, an element stabilizing the expression of mitogen-activated protein kinase 6 (MAPK6), thus activating the MAPK signaling pathway in lung squamous cell carcinoma." (PMID 37504305, 2023).
acute myeloid leukemia (2 papers, 2020 to 2021). Acute myeloid leukemia (AML) is a group of neoplasms arising from precursor cells committed to the myeloid cell-line differentiation. "Based on the information provided by the previous literatures, LINC00649 acted as an oncogene to facilitate the development of acute myeloid leukemia (AML), prostate cancer and colorectal cancer, but it was still unclear whether LINC00649 modulated GC progression in a similar manner." (PMID 33975517, 2021).
colorectal cancer (2 papers, 2021 to 2022). A primary or metastatic malignant neoplasm that affects the colon or rectum. "LINC00649 has verified its tumor-promoting effect in gastric cancer, colorectal cancer, BCa, etc." (PMID 36300088, 2022).
prostate carcinoma (2 papers, 2020 to 2021). A carcinoma that arises from epithelial cells of the prostate gland. "LINC00649 might participate in intracellular receptor signaling pathways in prostate cancer patients." (PMID 32579540, 2020).
cancer (3 papers, 2020 to 2022). A tumor composed of atypical neoplastic, often pleomorphic cells that invade other tissues. "Among all the cancer associated LncRNAs, LINC00649 gene located in chromosome 21 and contained 20 transcripts, which was poorly studied in the existed literatures, and our knowledge regarding to the biological functions of LINC00649 was seriously limited." (PMID 33975517, 2021). "The expression of LINC00649 in normal hematopoietic cells is the highest among all included cancers and tissues (TPM value = 12.83)." (PMID 32883226, 2020). "In contrast to our findings, LINC00649 expression was recently shown to be aberrantly low in AML patients, although in many other cancer types, high expression of LINC00649 has been shown to be crucial in driving carcinogenesis." (PMID 35565228, 2022). "Meanwhile, for most of cancers other than AML, expression level of LINC00649 in cancer cells is higher than that of corresponding normal tissues." (PMID 32883226, 2020). "Moreover, the expression of LINC00649 is much lower in AML cells in comparison with normal hematopoietic cells (TPM value 2.96 vs 12.83), which is converse in most of other cancer types." (PMID 32883226, 2020).
tumor (2 papers, 2021 to 2022). "We found that knockdown of LINC00649 expression in 5637 cells promoted the proliferation of 5637 cells.Our eight DEBMlncRNA risk models provide new insights into predicting prognosis, tumor invasion, and metastasis in BCa patients." (PMID 36300088, 2022).
LINC00649 also shares sentences with these, for which no sentence is quoted: cervical cancer (1 paper); COVID-19 (1); gastric cancer (1); oral squamous cell carcinomas (1); type II diabetes (1).